APOL1 (apolipoprotein L1)
Diseases named in the same sentence as APOL1 in open-access papers (continued):
Sharing a sentence is not in itself a finding about the gene and the disease.
kidney disease (continued). "Interestingly, evidence of association at the APOL1 locus was reduced in comparison to MYH9 (Pemp<0.045) despite impressive associations previously observed with kidney disease in African Americans." (PMID 24551085, 2014). "Furthermore, genetic investigations have clearly established that the genomic region containing APOL1 confers susceptibility to kidney disease." (PMID 24949636, 2014). "This hypothesized survival advantage of APOL1 variants suggests a potential mechanism for increased incidence and prevalence of kidney disease in patients of African descent." (PMID 25309811, 2012). "The increased propensity to HIV-related kidney disease in patients of African descent may be partially explained by recently discovered polymorphisms in apolipoprotein L-1 (APOL1) on chromosome 22 in Yoruban Africans." (PMID 25309811, 2012). "This evidence warrants future clinical trials to determine whether APOL1 could be used in clinical practice to identify high-risk individuals predisposed to kidney disease." (PMID 25309811, 2012). "Thus, the development of APOL1-associated nephropathy requires the presence of a second factor." (PMID 40027896, 2025). "Having established the platform-specific influence of APOL1, KLKB1, F12, and KNG1 variants on Olink and SomaLogic measurements of plasma APOL1, we investigated whether these variants may also be relevant to APOL1-associated pathologies, specifically kidney disease." (PMID 39975113, 2025). "Interestingly, only a minority of risk allele carriers develop APOL1-mediated kidney disease." (PMID 41010023, 2025). "To date, except for the neutral allele of ApoL1 G0 which is a major form discovered in humans, two human ApoL1 alleles have been identified, including ApoL1 G1 and ApoL1 G2, which are highly associated with various human kidney diseases in the population-based studies." (PMID 39669548, 2025). "Therefore, it remains unknown whether SARS-CoV-2 vaccination increases risk for kidney disease among patients who carry APOL1 HRG." (PMID 39291186, 2024). "APOL1 associated kidney diseases may be considered as an individual entity." (PMID 35408886, 2022). "The high burden of severe kidney disease (especially HIVAN/FSGS) attributable to APOL1 high-risk genotypes suggests that early HIV diagnosis and ART-initiation may be important strategies to reduce the risk of ESKD, particularly in people of West African and Caribbean ancestry." (PMID 35497797, 2022). "In addition, the presence of known risk factors for kidney disease, such as APOL1 risk variants, can also be challenging during donor evaluations, given that most individuals and allografts with these genetic variants will not experience kidney disease or allograft failure, respectively." (PMID 33847748, 2021). "Likewise, risk variants of renal disease in APOL1 associated with renal disease in west African populations are also found in the Americas as a result of the Transatlantic slave trade, differentially shaping the frequency spectrum of disease variants among Afro-descendent Latino populations." (PMID 35046991, 2021). "Intriguingly, G1 and G2 variants of apoL1, which are associated with increased kidney disease risk in humans, interact with and impair VAMP8 function in human cells leading to changes in autophagosome-lysosome fusion dynamics that may underlie the observed kidney pathology." (PMID 29346416, 2018). "Therefore, changing the splicing pattern of APOL1 risk variants to delete exon 4 may impair APOL1 secretion, prevent formation of the tripartite complex, and possibly mitigate the APOL1 kidney disease phenotype." (PMID 29880816, 2018). "Notably, these findings suggest that the unexplained mechanism by which APOL1 affects kidney-disease risk may involve HDLc." (PMID 22973513, 2012).
kidney disease (continued). "Recent studies show that APOL1 gene variants have a strong association withfocal segmental glomerulosclerosis, HIV-associated nephropathy, hypertensivenephrosclerosis, and lupus nephritis in African Americans." (PMID 41511474, 2026). "Awareness of APOL1-mediated kidney disease (AMKD) and participation in therapeutic trials remain low." (PMID 41774497, 2026). "Their involvement in APOL1-mediated kidney disease follows an autosomal recessive pattern of inheritance, meaning those heterozygous for either G1 or G2 variants (G1/G0 or G2/G0) do not carry an increased risk of developing kidney disease." (PMID 41010023, 2025). "It is important to note pre-clinical experiments supporting the development of therapeutics to treat APOL1 kidney disease, including those currently in clinical trials, were based on this two-hit, interferon-dependent model." (PMID 40940784, 2025). "Two high-risk APOL1 alleles (G1G1, G2G2, or G1G2) raise kidney disease risk significantly while inheriting one low-risk allele (G0G1 and G0G2) does not increase the risk of CKD." (PMID 40027896, 2025). "In this study, we present the first APOL1-mediated kidney disease (AMKD) model incorporating patient-derived induced pluripotent stem cells (iPSCs) with both homozygous G1G1 and G2G2 risk genotypes." (PMID 41043427, 2025). "Accordingly, we recommend incorporating APOL1 testing in the Proteinuric and Comprehensive Kidney Disease Panels to ensure an inclusive and equitable approach to genetic risk assessment." (PMID 40979400, 2025). "This study utilized induced pluripotent stem cells (iPSCs) derived from two patients homozygous for G1 and G2 to model human apolipoprotein L1 (APOL1)-mediated kidney disease (AMKD) in kidney organoids." (PMID 41043427, 2025). "In these populations, genetic predisposition to kidney disease and HIVAN is mediated through variants of the APOL1 gene, whereas sickle cell trait confers risk to milder forms of CKD." (PMID 39874132, 2025). "These APOL1 kidney diseases are overt and relatively rapid in onset, with nephrotic range proteinuria and with the severe FSGS pathology of glomerular collapse." (PMID 40940784, 2025). "Spijker and colleagues established a human model of APOL1-mediated kidney disease (AMKD) using kidney organoids generated from patient-derived iPSCs." (PMID 41043427, 2025). "The mechanism by which APOL1 RVs contribute to kidney disease remains a subject of active investigation." (PMID 41043427, 2025). "Over the past 15 years, how APOL1 risk variants cause injury to the kidney and how best to treat individuals with APOL1 kidney disease have been areas of intense research efforts." (PMID 40940784, 2025). "Since these diseases carry a common mechanistic driver, linking them as part of the spectrum of APOL1-mediated kidney diseases was logical." (PMID 40001508, 2025). "AMKDs are a group of kidney diseases that not only affect humans that are positive for two APOL1 RRVs." (PMID 40643483, 2025). "Further, APOL1 inhibition strategies are being tested in clinical trials of APOL1-mediated kidney diseases." (PMID 40459058, 2025). "Additionally, the APOL1 gene may interact with other genes to cause kidney disease." (PMID 40027896, 2025). "The potential for this pregnancy complication to have a significant impact on the presentation of APOL1 kidney disease and a comparison to the current disease paradigm of direct effects of APOL1 on kidney cells are the focus of this review." (PMID 40940784, 2025). "Connections between APOL1 genotype, kidney disease, and prematurity or low birth weight have been examined by multiple groups using the NEPTUNE, CKiD, and CureGN consortia." (PMID 40940784, 2025). "It is expected that this organoid model will provide a novel platform for studying the pathophysiology of APOL1-mediated kidney disease." (PMID 39056771, 2024).
kidney disease (continued). "This article takes a novel approach to leverage an SEM framework to identify challenges and sustainable opportunities to advance diversity for clinical study participation in apolipoprotein L1 (APOL-1)-mediated kidney disease." (PMID 40125376, 2024). "Ironically, the current study demonstrates that the same cation pore function of APOL1 G1 also drives podocyte injury and kidney disease." (PMID 38227370, 2024). "APOL1-mediated kidney disease is now recognized as one of the most common genetic kidney diseases in humans." (PMID 39271961, 2024). "Together, these results establish APOL1-mediated Na+/K+ transport as the proximal driver of APOL1-mediated kidney disease." (PMID 38227370, 2024). "Collectively, our results from multiple cohorts demonstrate IFN activity and EC-specific pyroptotic injury profiles in kidney disease in settings of APOL1 upregulation." (PMID 38838223, 2024). "Together, these results support our overarching conclusion that inhibition of APOL1 G1 monovalent-cation function is sufficient to prevent histological and clinical manifestations of APOL1-mediated kidney disease." (PMID 38227370, 2024). "This truncating variant contributed the most risk for CKD in patients monoallelic for APOL1 G1/G2, suggesting an epistatic interaction and a potential protective effect of wild-type APOL3 against APOL1-induced kidney disease." (PMID 39163132, 2024). "This set of variants included 6 pLOFs, 1 in-frame deletion, and 55 missense mutations, including both APOL1 G1 and G2 AFR-specific risk alleles for kidney disease." (PMID 39163132, 2024). "The mechanism by which RRVs induce cytotoxicity in experimental models is believed to mirror the pathomechanism of APOL1-mediated kidney disease." (PMID 38227370, 2024). "During the preparation of our current manuscript, the clinical efficacy of VX-147 in reducing proteinuria in APOL1-mediated kidney disease was reported." (PMID 38227370, 2024). "This phenomenon has also been observed in several pathogenic genes related to kidney disease, such as JAML and apolipoprotein L1." (PMID 38161229, 2024). "Here, we report a CRISPR-based genotyping assay and demonstrate its use in detecting two genetic variants in the Apolipoprotein L1 gene (APOL1), which are common among individuals of sub-Saharan African ancestry and greatly increase the risk of kidney disease." (PMID 39271961, 2024). "APOL1-mediated monovalent cation transport is a proximal driver of APOL1-mediated podocytopathy in kidney disease." (PMID 38227370, 2024). "To test the pathophysiologic relevance of APOL1 G1–mediated monovalent cation transport as the proximal driver of APOL1-mediated kidney disease in the in vivo setting, we generated APOL1 G1 transgenic mice." (PMID 38227370, 2024). "Because our study is based on experimental models, additional studies in human kidney tissue are required to validate the relevance of our results to human APOL1-mediated kidney disease." (PMID 38227370, 2024). "In a study by Freedman lab, kidney organoids model of APOL1 nephropathy were transcriptomically profiled." (PMID 39056771, 2024). "We conclude that both risk alleles affect similar key cell trafficking pathways, leading to reduced autophagy and suggesting new therapeutic targets to prevent APOL1 kidney diseases." (PMID 37969018, 2023). "Mice expressing the APOL1-G1 or APOL1-G2 risk allele in their podocytes display molecular, functional and structural podocyte changes, including foot-process effacement, that mimic the clinical features observed in patients with APOL1-induced kidney disease." (PMID 37969018, 2023). "Here we report on the strong protective effect of the APOL1 p.N264K missense variant against G2-mediated FSGS and kidney disease." (PMID 38036523, 2023). "Additional studies are needed at the basic and clinical levels before a comprehensive mechanism of APOL1-mediated kidney disease, a critical public health problem, is unraveled." (PMID 37461136, 2023).
kidney disease (continued). "Apolipoprotein L1 (APOL1) is expressed in the proximal tubular cells of healthy kidneys and is responsible for nearly 70% of the excess risk of kidney disease in people of African ancestry." (PMID 37872903, 2023). "Here, we review the reported paradigm and mechanisms for APOL1-mediated kidney disease and discuss the apparent shortcomings of this paradigm regarding clinically observed APOL1 disease." (PMID 37461136, 2023). "Most studies have shown the incidence of kidney disease in Black Africans and African Americans above other ethnicities due to the homozygous APOL1 – G1 and G2 genes, as G1/G1 is seen highest amongst our patient’s group (21.1%)." (PMID 36845824, 2023). "Studies have shown that APOL1 genetic variants are strongly associated with HIV-associated nephropathy, a quickly progressing kidney disease with severe tubular damage." (PMID 37872903, 2023). "APOL1 has been genetically validated as a target gene for kidney disease, and thus, pharmacologically regulating the expression of APOL1 at an individual level is an important problem." (PMID 36951457, 2023). "In the current study, we have used CRISPR/Cas9 genetic engineering to knock out or modify the sequence of endogenous APOL1 in RCC to mimic and examine the effects of these naturally occurring kidney disease risk allelic variants." (PMID 35159001, 2022). "APOL1 status interacted with SCT, and analyses stratified by APOL1 status indicated that the associations between SCT and kidney disease were largely restricted to individuals with APOL1 low-risk genotypes." (PMID 35257059, 2022). "APOL1 is mainly active in the kidney, and its high expression can promote the occurrence of kidney disease." (PMID 35090432, 2022). "Other manifestations of APOL1 kidney disease include shorter renal allograft survival among recipients with two APOL1 risk alleles and a rare but concerning gradual loss of kidney function among living kidney donors." (PMID 34765626, 2021). "As such, APOL1 expression in podocytes and endothelia should remain the focus for mechanistic studies in the APOL1-mediated kidney diseases." (PMID 34138902, 2021). "Prior to establishing its role in kidney diseases, APOL1 was known to protect against certain trypanosome species in humans and some primates." (PMID 34440683, 2021). "Despite relevance to both parasitic disease and kidney disease, direct structural characterization of the APOL1 channel has been challenging, likely due to the possible existence of multiple lipid-bound conformations and oligomerization states." (PMID 34331942, 2021). "In light of the significantly increased risk of HIVAN in carriers of two APOL1 risk alleles, a role in HIV infectivity has been postulated in the mechanism of APOL1 associated kidney disease." (PMID 34513880, 2021). "Using the mouse Nphs1 promoter, which is highly specific within kidney for podocytes, allowed targeting of APOL1-transgene expression to the cell where APOL1 is expressed in human kidneys and from where it is thought to drive APOL1-mediated kidney disease." (PMID 34765626, 2021). "It is imperative to elucidate the mechanism that prevents G0 cytotoxicity in order to understand how APOL1-mediated kidney disease manifests." (PMID 32427098, 2020). "Apolipoprotein L1 (APOL1), which accounts for almost 70% of the excess risk of kidney disease in individuals of African descent, is expressed in the proximal tubular cells in normal kidneys." (PMID 33066744, 2020). "This study will examine the increasing prevalence of kidney diseases in HIV-positive adults in a West African population, and the relationship between these diseases and the APOL1 high-risk genotype." (PMID 31182139, 2019). "In summary, this study will examine the increasing prevalence of kidney diseases in HIV-positive adults in a West African population, and the relationship between these diseases and the APOL1 high-risk genotype." (PMID 31182139, 2019).
kidney disease (continued). "We need to explore the differences in APOL1 variability among different races, in order to provide more information on future genetic studies on APOL1-related kidney disease." (PMID 28800731, 2017). "The present study confirms and extends the earlier observation that the association between HDLC and eGFR differs depending on rs73885319 genotype at the APOL1 kidney disease locus." (PMID 26025194, 2015). "The tandem APOL1 duplication was more common in kidney disease cases with an apparent G0G1 genotype than among controls with an apparent G0G1 genotype." (PMID 25933006, 2015). "In this study, we evaluated a cohort of young African Americans largely free of established CKD to examine the relation of APOL1, income and early kidney disease." (PMID 25884165, 2015). "This scalable and biologically informed approach provides a precision medicine framework for early intervention and may accelerate development of APOL1-targeted therapies to reduce kidney disease disparities." (PMID 41986737, 2026). "For example, pathogenic mutations in genes such as APOL1 and UMOD, which are associated with the onset of CKD, occur at varying frequencies across different ethnic groups, contributing to the disparities in kidney disease risk." (PMID 40069100, 2025). "Complicating this issue is the broad clinical spectrum of APOL1 kidney disease, which has engendered speculation that this reflects multiple mechanisms of kidney injury." (PMID 40940784, 2025). "Black Americans are 3–4 times more likely to develop nondiabetic kidney disease than other populations, and exonic risk variants in Apolipoprotein L1 (APOL1) drive much of this increased susceptibility." (PMID 39658338, 2025). "Preliminary clinical data suggest that it may even mitigate the progression of APOL1-mediated kidney diseases in proteinuric patients." (PMID 40643483, 2025). "Further investigation examining the pathways linking DNA variants, DNA methylation and APOL1 variant expression to CKD in APOL1 high-risk genotypes, within and outside of the setting of HIV, is likely to provide better insights into the development of kidney disease in this patient population." (PMID 39448372, 2025). "Its function in kidney disease is currently unknown and may represent a novel pathway of CKD in people with HIV and APOL1 high-risk genotypes." (PMID 39448372, 2025). "The mechanism of APOL1-mediated kidney diseases follows a “2-hit” process." (PMID 41278320, 2025). "However, only a minority of individuals of African ancestry carrying APOL1 RRVs develop kidney disease, suggesting that additional genetic or environmental modifiers are involved." (PMID 41010023, 2025). "Apolipoproteins, such as Apol1, play important roles in renal functions and kidney diseases." (PMID 40542844, 2025). "Alternatively, APOL1 kidney disease also may present as an insidious, slowly progressive disease, with less proteinuria but losses in glomerular filtration rate and with varied pathology." (PMID 40940784, 2025). "Further studies showed that background haplotype variation could confer enhanced risk or protection from APOL1 association with kidney disease, with the emergence of a new category of etiologies of CKD termed APOL1-Mediated Kidney Disease (AMKD)." (PMID 40001508, 2025). "As approximately 15% of individuals with an APOL1 high-risk genotype will develop ESKD, identifying genetic modifiers for the risk variants can improve our understanding of the incomplete penetrance seen in APOL1 kidney disease." (PMID 39658338, 2025). "Of note, interferon type I produced in this setting inhibits infection of other monocytes by DENV through progressive activation of the JAK/STAT pathway.S11,S12 In this scenario, viral recognition and immunologic response to DENV activate common pathways to APOL1-mediated kidney diseases." (PMID 41278320, 2025). "The current theory is APOL1 kidney disease pathogenesis is a two-hit mechanism." (PMID 40940784, 2025).